AP5Z1 (adaptor related protein complex 5 subunit zeta 1)
Description:
As part of AP-5, a probable fifth adaptor protein complex it may be involved in endosomal transport. According to PubMed:20613862 it is a putative helicase required for efficient homologous recombination DNA double-strand break repair.
Synonyms: KIAA0415; SPG48; zeta
Tractability: PROTAC: ubiquitination databases record sites on it; its protein half-life has been measured.
Gene: Protein-coding gene on chromosome 7 (4,775,615 to 4,794,397, forward strand). Ensembl gene ENSG00000242802.
Subcellular location: Cytoplasm; Nucleus
Subcellular location (Human Protein Atlas): Nuclear speckles; Nucleoplasm
Gene Ontology:
Molecular function: protein binding
Biological process: double-strand break repair via homologous recombination; endosomal transport; lysosome organization; vesicle-mediated transport
Cellular component: cytoplasm; nuclear speck; nucleoplasm; nucleus; AP-5 adaptor complex; AP-type membrane coat adaptor complex; late endosome; lysosome
Genetic constraint (gnomAD): Loss-of-function variants: 108 observed, 77.23 expected, observed/expected ratio (o/e) 1.4, 90% interval 1.2 to 1.64. The synonymous counts are far from expectation, so gnomAD's model fits this gene poorly and the ratio says little. Missense variants: 1,565 observed, 1,028.7 expected, observed/expected ratio (o/e) 1.52, 90% interval 1.46 to 1.59. Synonymous variants: 751 observed, 493.31 expected, observed/expected ratio (o/e) 1.52, 90% interval 1.43 to 1.62.
Gene-disease validity (ClinGen):
ClinGen rates the evidence that AP5Z1 causes each of these diseases.
hereditary spastic paraplegia (autosomal recessive): Definitive. Hereditary spastic paraplegias (HSP) comprise a genetically and clinically heterogeneous group of neurodegenerative disorders characterized by progressive spasticity and hyperreflexia of the lower limbs.
Homologues: Orthologues: chimpanzee AP5Z1 (99% identical), dog AP5Z1 (79% identical), guinea pig AP5Z1 (79% identical), mouse Ap5z1 (79% identical), rat AABR07035428.2 (77% identical), pig AP5Z1 (77% identical), rabbit AP5Z1 (73% identical), macaque AP5Z1 (59% identical), zebrafish ap5z1 (53% identical), Drosophila melanogaster Lpin (14% identical), Caenorhabditis elegans lpin-1 (11% identical). Paralogues in human: LPIN3 (15% identical), LPIN1 (15% identical), LPIN2 (14% identical).
Diseases named in the same sentence as AP5Z1 in open-access papers:
AP5Z1 is named in the same sentence as 18 diseases in open-access papers, as found by Europe PMC text mining. Sharing a sentence is not in itself a finding about the gene and the disease. The quoted sentences say what the papers report.
hereditary spastic paraplegia (6 papers, 2010 to 2023). "Spatacsin interacts with spastizin and AP5Z1, 2 proteins encoded by genes mutated in other forms of hereditary spastic paraplegia, SPG15 and SPG48, respectively." (PMID 37871017, 2023). "However, it is clearly important in humans, because mutations in its ζ subunit, encoded by the AP5Z1 gene (aka SPG48), cause hereditary spastic paraplegia (HSP), as do mutations in either SPG11 or SPG15 (SPG is an acronym for spastic paraplegia gene)." (PMID 29381698, 2018). "Mutations in AP5Z1, encoding a subunit of the AP-5 complex, have been reported to cause hereditary spastic paraplegia (HSP), although their impact at the cellular level has not been assessed." (PMID 26085577, 2015).
Spastic paraplegia (6 papers, 2010 to 2023). Complete loss of the ability to move the lower limbs accompanied by spasticity of the lower limbs. "Intriguingly, recessive mutations in a component of the core AP5 complex (SPG48/AP5Z1) also cause a very similar clinical phenotype to SPG11/15 mutations, with cognitive defects, thin corpus callosum and spastic paraplegia." (PMID 25480570, 2015). "SPG48 patients have some clinical features similar to those of SPG11 or SPG15 patients, including spastic paraplegia, retinal abnormalities and parkinsonism, but the clinical spectrum of AP5Z1 patients is still being defined." (PMID 26085577, 2015).
Parkinsonism (3 papers, 2015 to 2023). Characteristic neurologic anomaly resulting from degeneration of dopamine-generating cells in the substantia nigra, a region of the midbrain, characterized clinically by shaking, rigidity, slowness of movement and difficulty with walking and gait. "The 7p22.1 mutation in Adaptor Related Protein Complex 5 Subunit Zeta 1 (SPG48/AP5Z1), facilitating intracellular transmembrane proteins sorting and trafficking cargos through vesicles, results in motor and sensory neurons neuropathy, ataxia, parkinsonism, and cognitive impairments." (PMID 35163618, 2022).
macular degeneration (1 paper, 2026). Loss of vision in the central portion of the retina (macula), secondary to retinal degeneration. "Five unrelated patients from Europe and Iran were identified with a distinctive macular degeneration associated with bi-allelic variants in AP5Z1 (HGNC: 22197) and AP5B1 (HGNC: 25104), subunits of the vesicular fifth adaptor protein (AP-5) complex." (PMID 41830174, 2026).
retinal disease (1 paper, 2025). "In summary, through a large multi-national collaborative effort involving multiple centers, we have identified pathogenic variants in the genes AP5Z1, AP5M1, and AP5B1 as an independent cause of a recessive form of retinal disease characterized by the progressive loss of macular photoreceptors." (PMID 40081374, 2025).
AP5Z1 also shares sentences with these, for which no sentence is quoted: Cognitive impairment (2 papers); Alexander disease (1); Ataxia (1); Autosomal recessive spastic paraplegia type 48 (1); infection (1); Infertility (1); Intellectual disability (1); Mitochondrial encephalopathy (1); neuropathy (1); optic atrophy (1); peripheral neuropathy (1); psoriasis (1); retinal degeneration (1).